FAM47A (family with sequence similarity 47 member A)
Synonyms: MGC27003
Tractability: PROTAC: ubiquitination databases record sites on it.
Gene: Protein-coding gene on chromosome X (34,129,752 to 34,132,314, reverse strand). Ensembl gene ENSG00000185448.
Gene Ontology:
Molecular function: protein binding
Homologues: Orthologues: macaque FAM47A (84% identical), Drosophila melanogaster Frl (14% identical), Caenorhabditis elegans daam-1 (13% identical), Caenorhabditis elegans frl-1 (12% identical), Drosophila melanogaster dia (11% identical), zebrafish fmn2b (10% identical), Caenorhabditis elegans fhod-1 (10% identical), Caenorhabditis elegans exc-6 (10% identical), Drosophila melanogaster capu (10% identical), Drosophila melanogaster form3 (10% identical), zebrafish fhdc2 (8% identical), Caenorhabditis elegans cyk-1 (8% identical), and 1 more. Paralogues in human: FAM47C (67% identical), FAM47B (55% identical), FMNL2 (16% identical), DIAPH1 (15% identical), FMNL1 (15% identical), DIAPH3 (14% identical), FMNL3 (14% identical), DIAPH2 (14% identical), INF2 (13% identical), DAAM1 (13% identical), DAAM2 (12% identical), FHOD3 (12% identical), and 6 more.
Diseases named in the same sentence as FAM47A in open-access papers:
FAM47A is named in the same sentence as 2 diseases in open-access papers, as found by Europe PMC text mining. Sharing a sentence is not in itself a finding about the gene and the disease. The quoted sentences say what the papers report.
Central hypothyroidism (1 paper, 2023). A type of hypothyroidism due to an insufficient stimulation of an otherwise normal thyroid gland. "FAM47A and TFE3 were potential risk genes for hypertension, whereas IRS4, an insulin signaling-pathway gene associated with central hypothyroidism, potentially linked with cardiac defects." (PMID 37800145, 2023).
FAM47A also shares sentences with these, for which no sentence is quoted: Hypertension (1 paper).